ZNF81 (zinc finger protein 81)
Description:
May be involved in transcriptional regulation.
Synonyms: HFZ20; MRX45; dJ54B20.6
Tractability: PROTAC: UniProt records ubiquitination sites on it; ubiquitination databases record sites on it.
Gene: Protein-coding gene on chromosome X (47,836,471 to 48,002,561, forward strand). Ensembl gene ENSG00000197779.
Subcellular location: Nucleus
Gene Ontology:
Molecular function: DNA-binding transcription factor activity, RNA polymerase II-specific; RNA polymerase II cis-regulatory region sequence-specific DNA binding; sequence-specific double-stranded DNA binding
Biological process: regulation of transcription by RNA polymerase II; regulation of DNA-templated transcription
Cellular component: nucleus
Gene-disease validity (ClinGen):
ClinGen rates the evidence that ZNF81 causes each of these diseases.
X-linked intellectual disability (X-linked): Disputed. An X-linked intellectual deficiency in which not enough information is known, reported or published to indicate whether a gene causes non-syndromic or syndromic presentations.
Homologues: Orthologues: chimpanzee ZNF81 (99% identical), macaque ZNF81 (98% identical), pig ZNF81 (88% identical), rabbit ZNF81 (84% identical), dog ZNF81 (84% identical), guinea pig ZNF81 (82% identical), rat Znf81 (66% identical). Paralogues in human: ZNF41 (42% identical), ZNF585B (39% identical), ZNF175 (39% identical), ZNF484 (39% identical), ZNF658 (38% identical), ZNF585A (38% identical), ZNF33B (37% identical), ZNF182 (37% identical), ZNF30 (36% identical), ZNF708 (36% identical), ZNF605 (35% identical), ZNF7 (35% identical), and 164 more.
Diseases named in the same sentence as ZNF81 in open-access papers:
ZNF81 is named in the same sentence as 5 diseases in open-access papers, as found by Europe PMC text mining. Sharing a sentence is not in itself a finding about the gene and the disease. The quoted sentences say what the papers report.
developmental delay (2 papers, 2015 to 2024). "In a comparative genomic hybridization (CGH) array analysis a duplication of SPACA5 (and ZNF81/ZNF182) has been described in a boy with developmental delay, autistic features, and growth and speech delay." (PMID 25984793, 2015). "A 335.4-kb duplication in the Xp11.2p11.3 region, which contains the C2H2 zinc finger proteins, ZNF81 and ZNF182, was identified in a patient showing developmental delays, autistic features, and growth and speech delays." (PMID 38830862, 2024).
Intellectual disability (2 papers, 2021 to 2024). "ZNF81 is a member of the zinc finger gene family and encodes a protein that likely functions as a transcription factor, and germline mutations in this gene cause an X-linked form of intellectual disability (MRX45)." (PMID 38321229, 2024). "His X-linked intellectual disability panel was notable for four potential disease-causing variants (in each of ATRX, FANCB, ZNF81, and ARX), but all were of undetermined significance." (PMID 34575122, 2021).
ZNF81 also shares sentences with these, for which no sentence is quoted: speech delay (2 papers); cognitive deficit (1); schizophrenia (1).